CD96 (CD96 molecule)
Diseases named in the same sentence as CD96 in open-access papers (continued):
Sharing a sentence is not in itself a finding about the gene and the disease.
infection (7 papers, 2012 to 2025). The state of being infected such as from the introduction of a foreign agent such as serum, vaccine, antigenic substance or organism. "Our data demonstrate that this is a conserved and independent function of several primary HIV-1 Nef and Vpu alleles and CD96 downmodulation is also observable upon infection with primary patient-derived HIV-1 variants." (PMID 40911682, 2025). "CD96+ patients tend to have a lower complete remission rate after induction chemotherapy and higher infection and relapse rates compared with CD96− patients." (PMID 39445003, 2024). "Clearly, further studies of human NK cells, ex vivo and in the context of infection, are needed to define the role of nectin-1, and CD96, in NK cell defense against HSV." (PMID 30759143, 2019). "Reduced CD96−CD226+ cells and elevated CD96+CD226− cells among NK cells especially TIGIT−NK cells, had opposite associations with viral load in the first month of infection, as well as CD4 T-cell counts in including the twelfth month and more than 2 years of chronic infection." (PMID 33717085, 2021). "Moreover, since gD and CD96 have similar affinity for nectin-1 a competition between the two ligands may occur during infection." (PMID 30759143, 2019). "Further, at different stages of infection, CD96−CD226+ cells diminished among total NK cells, TIGIT+NK and TIGIT−NK cells, while CD96+CD226− cells expanded." (PMID 33717085, 2021). "However, upon infection with HIV-1, as expected, CD96 was less prominent at the cell surface but rather sequestered to internal compartments including the Golgi, TGN, and lysosomes." (PMID 40911682, 2025). "Additionally, at different stages of infection, CD96−CD226+ cells among NK cells, TIGIT+NK and TIGIT−NK cells significantly diminished, while CD96+CD226− cells expanded (all P < 0.05)." (PMID 33717085, 2021). "The opposite associations between HIV-1 viral load and the amounts of these two NK subset cells in the first month of infection indicate that diminished CD96−CD226+NK cells and expanded CD96+CD226−NK cells could play an antagonistic role." (PMID 33717085, 2021). "CD96+CD226+ cells among NK cells especially TIGIT+NK cells did not significantly expand at different stages of infection, while these cells among TIGIT−NK cells increased in the first month of infection and in chronic infection over 2 years (all P < 0.05)." (PMID 33717085, 2021). "Therefore, the modulation of CD96 in productively HIV-1–infected CD4+ T cells may provide critical insights into its role in human immunobiology and lever our understanding of its role in T cell signaling and regulation, especially in the context of infection and inflammation." (PMID 40911682, 2025). "In addition, depletion of CD96 from CD4+ T cells did not alter basic parameters of virus replication, i.e., infection rate, virus production, and HIV-1 infectious particle release, even when Nef and Vpu were inactivated rendering the virus inactive in CD96 down-regulation." (PMID 40911682, 2025).
inflammation (1 paper, 2019). Aberrant reaction of the microcirculation characterized by movement of fluid and leukocytes from the blood into extravascular tissues. "Interestingly, augmented IL9 along with low CD96 and DPP4 expression observed in UC relative to CD mimics a Th9 pro-inflammatory profile associated with chronic intestinal inflammation in mice." (PMID 31191543, 2019).
CD96 also shares sentences with these, for which no sentence is quoted: lung carcinoma (5 papers); colitis (2); myeloma (2); sarcoma (2); ankylosing spondylitis (1); astrocytoma (1); bladder cancer (1); brain cancer (1); cholangiocarcinoma (1); chronic myeloid leukemia (1); co-infection (1); endocervical adenocarcinoma (1); esophageal carcinoma (1); hair diseases (1); Immunodeficiency (1); inflammatory bowel disease (1); kidney cancer (1); lung squamous cell carcinoma (1); lymphoma (1); mantle cell lymphoma (1); myeloid leukemia (1); oligoastrocytoma (1); oligodendroglioma (1); osteoporosis (1); ovarian serous cystadenocarcinoma (1); ovarian tumour (1); pancreatic adenocarcinoma (1); prostate adenocarcinoma (1); rectal cancer (1); rectum adenocarcinoma (1).
A further 7 diseases each share a sentence with CD96 in 1 paper.